INS (insulin)
Diseases named in the same sentence as INS in open-access papers (continued):
Sharing a sentence is not in itself a finding about the gene and the disease.
Insulin resistance (continued). "Although serum insulin was not determined in this study, it is known that hyperinsulinaemia accompanied by inflammation in insulin-sensitive tissues and insulin resistance (IR) are the main metabolic abnormalities in obese patients." (PMID 32388582, 2021). "Ponies and Andalusian horses are known to release more insulin in response to a similar dietary intake of NSC (either simple sugars, fructans or starch) compared with Standardbreds; and are more prone to tissue insulin resistance, which further promotes hyperinsulinaemia." (PMID 35051099, 2021). "Treatment with vupanorsen also resulted in 55 % reduction in adipose tissue insulin resistance index, while other insulin sensitivity indices and HbA1c levels were not changed." (PMID 34865644, 2021). "Interestingly, at age 31 years, the women with elevated T displayed significantly increased insulin resistance and secretion (expressed as greater HOMA-B, HOMA-IR, and insulin values) compared with the normoandrogenic women, independently of BMI." (PMID 34153097, 2021). "DM can be classified into type 1 DM (T1D) and type 2 DM (T2D); the former primarily results from a lack of insulin secretion, whereas the later results from insulin resistance, which can lead to impaired insulin secretion." (PMID 33430527, 2021). "Together, these data suggest that, due at least in part to enhanced insulin secretion, adult Csn2WT/K70E mice develop early signs of type II diabetes, including congenital hyperinsulinism, insulin resistance, and obesity, though not yet diabetic." (PMID 33911083, 2021). "In this study, indirect methods including fasting blood sugar (FBS), fasting insulin (FI), FBS/FI ratio, and quantitative insulin sensitivity check index (QUICKI) were compared with the homeostasis model assessment of insulin resistance (HOMA-IR) as a standard technique." (PMID 34458674, 2021). "Finally, HFD-feeding induced insulin resistance and abnormal glucose metabolism, as shown by the high serum insulin concentration and HOMA-IR, but this insulin resistance was significantly ameliorated by resveratrol treatment." (PMID 34257688, 2021). "Conversely, other interventional studies have shown that long-term niacin supplementation can lead to insulin resistance; thus, it may exacerbate NAFLD's already reduced insulin sensitivity." (PMID 34522493, 2021). "Although insulin secretion basically worsened, insulin resistance did not develop in the F2 and F3 offspring because of sex-specific modifications." (PMID 34209784, 2021). "Saturated fats can also directly induce insulin resistance in peripheral and hypothalamic cells in the absence of high insulin levels." (PMID 34831343, 2021). "The Goto-Kakizaki (GK) rat, a commonly used insulin-resistant type 2 diabetic model for the study of non-obese T2D, is characterized by abnormalities in insulin secretion, glucose metabolism and chronic inflammation." (PMID 34575050, 2021). "Patients with severe insulin resistance (SIRD) characterised by a higher BMI and prevalence of NAFLD may benefit most from treatments that reduce body weight and improve insulin sensitivity." (PMID 33387681, 2021). "“Insulin resistance” does not apply equally to all of insulin’s actions, however, as evidenced by differences between simple insulin deficiency and IR." (PMID 33901270, 2021). "In contrast, insulin-stimulated Akt phosphorylation was strongly reduced in WAT, muscle, and liver, indicating the development of insulin resistance in peripheral tissues of TnTp38γ/δact mice (in line with the higher circulating levels of NEFAs and triglycerides in these mice)." (PMID 34758018, 2021). "Ex-4 was reported to improve neuronal insulin resistance both in vivo and in vitro experiments by preventing pathological phosphorylation of IRS-1, which interferes with its function to activate the downstream signaling cascade of insulin." (PMID 33616807, 2021).
Insulin resistance (continued). "Moreover, in a mouse model of obesity and insulin resistance, the inducible GRK2 ablation reverts the insulin-resistant and obese phenotype." (PMID 33467677, 2021). "As hepatic insulin signaling positively regulates hepatic DNL, the condition in NAFLD wherein insulin fails to suppress gluconeogenesis but continues to activate DNL is referred to as “selective hepatic insulin resistance”." (PMID 33923817, 2021). "T2DM is characterized by insulin resistance, in which the body usually does not fully respond to insulin." (PMID 34679681, 2021). "In patients with the AA genotype of NOS1AP rs12742393, the drug showed better efficacy with respect to levels of fasting plasma glucose (FPG), fasting serum insulin (FINS), HOMA-B and homeostasis model assessment for insulin resistance (HOMA-IR) than in patients with the AC + CC genotype (P < 0.05)." (PMID 34772419, 2021). "We sought to assess the residual effects (post 72-h training cessation) on fasting plasma glucose (FPG) and fasting insulin (FI) after 12-weeks of high-intensity interval training (HIIT), resistance training (RT), or concurrent training (CT) in women with insulin resistance (IR)." (PMID 34858210, 2021). "Under the insulin resistance state, insulin does not inhibit gluconeogenesis; instead, it paradoxically over-activates adipogenesis, which leads to a fatal combination of hyperglycemia and hypertriglyceridemia." (PMID 34938205, 2021). "Changing BCAA levels are commonly interpreted with respect to insulin resistance and T2D in obesity-related studies; however, the T2D rates and insulin levels here do not support these as possible factors." (PMID 34822395, 2021). "Obesity as expected did not modify fasting glycemia, but increased plasma insulin levels by 119% and induced insulin resistance, as observed by an increase of 148% in HOMA-IR." (PMID 34439481, 2021). "While these results do not negate a role for GPR109a signaling in niacin-induced insulin resistance, they suggest that endogenous GPR109a signaling does not affect glucose tolerance or glucose-stimulated serum insulin." (PMID 33924461, 2021). "While this study did not examine whether insulin-mediated attenuation of autophagy was affected by HI/HG, treatment of L6 skeletal muscle myotubes with palmitate (a saturated fatty acid known to cause insulin resistance), prevented insulin-induced inhibition of autophagy at low doses." (PMID 34336862, 2021). "We studied the effect of 3 months concomitant LNS and ART intake on glucose and insulin metabolism and found that LNS led to more insulin resistance, higher glucose and HbA1c, which potentially could lead to metabolic disorders." (PMID 34657634, 2021). "In contrast, 12 weeks supplementation of dietary nicotinamide riboside did not improve insulin sensitivity and other metabolic parameters in obese insulin resistance men." (PMID 34182970, 2021). "Similarly to the emerging systemic insulin resistance observed in VDD treatment groups, compromised insulin-dependent vasodilation was registered." (PMID 33791074, 2021). "5- and 9-PAHSAs also augment glucose-stimulated insulin and glucagon-like peptide-1 secretion in young chow-fed mice and mice with insulin resistance due to aging but not in HFD-fed mice." (PMID 34418413, 2021). "The values for Homeostatic Model Assessment of Insulin Resistance (HOMA - IR) and Homeostatic Model Assessment of islet β cell function (HOMA - β) were determined from fasting plasma glucose and insulin concentration (Electrochemiluminescence, Cobas e602, Germany)." (PMID 34579668, 2021). "HOMA (Homeostatic model of assessment) model was used to estimate Beta cell secretion (HOMA-B) and insulin resistance (HOMA-IR); while the Disposition index {(DI) hyperbola product of insulin sensitivity (1/HOMA-IR) and beta cell secretion} was used to estimate the beta cell function." (PMID 33602978, 2021).
Insulin resistance (continued). "The subsequent changes in insulin signaling, especially IRS-1, indicate that the link between the adipose tissue and skeletal muscle plays a critical role in the improvement of HFD-induced muscular insulin resistance by d-allulose in Wistar rats." (PMID 34684891, 2021). "First, although the fasting blood glucose level and glucose clearance during OGTT in the KD(72%) mice were similar to those in the NC group, the secretion of insulin was significantly higher in the KD(72%) mice, and the KD(72%) mice also had a higher HOMA-IR index and insulin resistance index." (PMID 33785628, 2021). "The higher insulin resistance observed in women with hypertriglyceridemia was accompanied by higher basal and total insulin secretion, although lower ISSI-2 index indicated insufficient compensation of insulin secretion for the observed degree of insulin resistance." (PMID 33387029, 2021). "Overall, males had greater fasting glucose and insulin levels (S, p < 0.01 for both), and greater Adipo-IR (i.e., surrogate measure of adipocyte insulin resistance), but there were no sex by treatment interactions." (PMID 34943961, 2021). "In fact, Yan et al160 found that LCN2 expression in adipocytes leads to insulin resistance in adipocytes, and that LCN2 could control insulin sensitivity in patients with obesity." (PMID 33945675, 2021). "Although in our study, TGI was considered a marker for insulin resistance, there might be some heterogeneities in reflecting insulin resistance when measured in terms of TGI compared with HOMA-IR, which considers the serum insulin level." (PMID 34944602, 2021). "Initially, in T2D patients, insulin is regularly produced but it is not able to stimulate the signaling, thus establishing a condition known as insulin resistance." (PMID 34681954, 2021). "The absence of this pathway will lead to peripheral insulin resistance, which is mainly manifested by an increase in systemic insulin levels and a decrease in insulin sensitivity." (PMID 34016950, 2021). "This suggests that metabolic and microvascular insulin responses are important predictors of one another, but most metabolic insulin resistance predictors do not predict microvascular insulin responses." (PMID 34075130, 2021). "Since nanoparticles made from total lipids extracted from H-Exo have a similar effect as H-Exo on insulin-mediated glucose uptake by hepatocytes, the effects of H-Exo proteins and RNAs in insulin resistance were not further investigated in this study." (PMID 33431899, 2021). "Taken together, the high levels of glucose, insulin, and IGF-1, which result from insulin resistance, may be connected to the onset of obesity, metabolic syndrome, cardiovascular diseases, and others chronic diseases, by unsettling basic metabolic processes." (PMID 34243726, 2021). "Despite the lack of significant changes in glucose levels, insulin levels in the obese group were significantly higher, as were measures of insulin resistance (HOMA-IR)." (PMID 34440238, 2021). "Despite a significant correlation between sphingolipids, mitochondrial dysfunction, insulin resistance and T2D, this subject has not received much attention compared to the direct effect of sphingolipids on the insulin signaling pathway." (PMID 33815291, 2021). "Although insulin resistance in skeletal muscle is the primary defect in type 2 diabetes, and dysregulation of INSR splicing occurs in the insulin target tissues of patients with insulin resistance, the role of INSR splicing in the pathogenesis of type 2 diabetes is unclear." (PMID 34063658, 2021). "The mechanism by which metformin, an insulin-sensitizing drug, reduces the testosterone level in women with PCOS may involve improvement in peripheral insulin resistance." (PMID 34053455, 2021). "Under conditions of hepatic insulin resistance, insulin fails to suppress HGP, while keeps promoting DNL, leading to hyperglycemia, hypertriglyceridemia, and hepatic steatosis." (PMID 34572151, 2021).
Insulin resistance (continued). "Glucose tolerance testing and insulin tolerance testing revealed that eritoran did not improve systemic insulin resistance." (PMID 34205789, 2021). "In both groups the following investigations were performed: fasting glucose and insulin levels, Homeostatic Model Assessment for Insulin Resistance (HOMA-IR), 75 g five-hour Oral Glucose Tolerance Test (OGTT) with an assessment of glucose and insulin and lipid profile evaluation." (PMID 33916952, 2021). "T2DM is a form of diabetes characterized by high blood sugar, insulin resistance, and a relative lack (although not complete absence) of insulin." (PMID 33668426, 2021). "In summary, in this cohort with overweight/obese subjects without T2D and a varying degree of insulin-resistance, plasma ImP concentrations were positively correlated with diastolic blood pressure but not with insulin-sensitivity." (PMID 34444866, 2021). "Negative correlation was seen between rs1137101 and triglycerides in Tunisians, while homeostasis model assessment of insulin resistance (HOMA-IR) and insulin correlated with rs2025804 and rs1137101 among Bahraini subjects, and rs1137101 correlated with estradiol and prolactin." (PMID 33245096, 2021). "The goal of this review was to reveal the relationship of vitamin D status and fasting plasma insulin as a measure of insulin resistance in previous diabetic and non-diabetic observational studies." (PMID 34063822, 2021). "Furthermore, homeostatic model assessment for insulin resistance (HOMA-IR) (q < 0.001) and insulin (q < 0.01) levels correlated with Ra-supp." (PMID 33924347, 2021). "Some studies showed the relationship between the presence of T allele TCF7L2 rs7903146 and enhanced protein expression, compromised insulin secretion, impaired incretin effects and hepatic insulin resistance, however, other studies did not support these data." (PMID 33810367, 2021). "Moreover, these species are inversely correlated to obesity (BMI), insulin resistance (HOMA-IR, fasting insulin) and also dysglycemia (HbA1c)." (PMID 34684461, 2021). "To investigate our hypothesis that hepatic lipid accumulation drives hyperinsulinemia and insulin resistance by altering HVAN activity, we set out to test if obesity-induced insulin dysregulation is dependent on an intact hepatic vagal nerve." (PMID 34192533, 2021). "Consistent with reduced insulin resistance, AAV-Notum mice exhibited improved glucose tolerance, although we were unable to demonstrate statistically significant differences in insulin sensitivity by ITT, likely due to the relatively modest effect of Notum on this trait." (PMID 34385484, 2021). "Although the earliest study observed that the expression of ANGPTL8 increased in the state of insulin resistance, with the progress of follow-up studies, people realized that insulin, rather than insulin resistance, promoted the expression of ANGPTL8." (PMID 34582711, 2021). "Inline, sRANKL was correlated with glucose intolerance based on blood glucose levels (r = 0.174, p = 0.003) at ICU admission but we did not detect differences regarding long-term markers of insulin resistance (HbA1c, insulin) or dyslipidemia (cholesterol)." (PMID 35054232, 2021). "An increase in adipokines resistin, leptin, PAI-1 and retinol-binding protein 4 in patients with metabolic syndrome and T2D induce insulin resistance in megakaryocytes by interfering with IRS-1 expression, therefore overcoming the inhibitory effects of insulin on platelets." (PMID 34943862, 2021). "Metabolically, when the effects of the two interventions were combined (NoPA and HFD), the rats of group 4 demonstrated a significantly higher mean insulin level and HOMA‐IR index than that of group 1; this metabolic pattern is suggestive of insulin resistance." (PMID 33904660, 2021). "Besides, glucose, insulin levels, homeostatic model assessment for insulin resistance (HOMA-IR) and quantitative insulin sensitivity check index (QUICKI) were also measured." (PMID 34444289, 2021).
Insulin resistance (continued). "For dysglycemia/insulin resistance linked variables, there were negative correlations of OGIS index with FPG, AUCg, and plasma insulin OGTT in all and the highly overweight and obese subject group." (PMID 34371884, 2021). "Glucose and insulin levels increased significantly, and to the same extent, with HFD-feeding compared with chow in both genotypes, which confirms that C57Bl6/N mice also are prone to rapidly develop obesity and insulin resistance on a high fat diet." (PMID 34630160, 2021). "Some studies have shown that miRNA-146a may reduce insulin resistance by activating JNK and P38 MAPK pathways which can play a major role in insulin signaling pathway." (PMID 34077450, 2021). "Interestingly, exposure to HFD led to the overactivation of insulin in the VMH, leading to a reduction in SF1 neurons firing frequency, in comparison to the insulin resistance induced in ARC neurons." (PMID 34201257, 2021). "Palmitate (0.8 mM and 0.6 mM) induced insulin resistance in C2C12 myotubes, suppressed the insulin-stimulated phosphorylation of downstream target proteins, increased AA concentration (all p values < 0.0001), increased pro-inflammatory cytokines (TNF-α and IL6), and reduced GLUT4 mRNA expression." (PMID 34209599, 2021). "Nevertheless, it is interesting to note that the increase BMI and insulin were not accompanied by significant increases in HOMAIR, indicating a lack of association with insulin resistance." (PMID 33909378, 2021). "Furthermore, in addition to BMI, our neurological cases were characterized by significantly higher levels of glucose, fasting insulin and HOMA levels, indicating insulin resistance." (PMID 34835999, 2021). "Clusterin can also directly affect insulin signaling and inflammation, two factors that can lead to insulin resistance, via its actions on macrophage phosphoinositide 3-kinase (PI3K; a mediator of insulin signaling) and NFκB (a major pro-inflammatory pathway in insulin resistance)." (PMID 33717095, 2021). "Since insulin resistance in T2DM decreases glucose uptake and sortilin is a major component of GSVs, we evaluated sortilin in 3T3L1 adipocytes under conditions rendering it resistant to insulin action." (PMID 33498179, 2021). "Knockdown of SIRT2 in insulin-resistant cells ameliorates insulin sensitivity in mouse muscle cells; however, knocking out SIRT2 in mice could exacerbate insulin resistance in muscle cells." (PMID 33806509, 2021). "Insulin resistance (IR) is a condition that can be described as a lack of insulin effects on selected tissues, mostly due to impaired post-receptor signaling pathways." (PMID 34204938, 2021). "It is noteworthy that low intracellular Mg2+ impairs cell responsiveness to insulin, because low intracellular Mg2+ alters the tyrosine-kinase activity of the insulin receptor (INSR), leading to the development of post-receptor insulin resistance and decreased cellular glucose utilization." (PMID 33499378, 2021). "In contrast, IR deletion in brown adipocytes leads to a decrease in insulin secretion and a progressive glucose intolerance but without insulin resistance." (PMID 33435513, 2021). "The cause of the disease is either the lack of insulin production (Type 1, T1) or decreased insulin production combined with an acquired insulin resistance of the organism (Type 2, T2), with the latter type accounting for ca. 90% of all patients." (PMID 34209125, 2021). "In contrast, under high‐fat diet (HFD) feeding conditions, glucose tolerance and insulin resistance were exacerbated with no alteration of either insulin secretory capacity or body weight in male, but not in female, Dusp8‐KO mice." (PMID 33943029, 2021). "We detected WAT insulin resistance after only 7 days of HFD feeding, with reduced insulin-mediated WAT glucose uptake and suppression of WAT lipolysis, which was accompanied by impaired activation of key insulin signaling steps initiating at the level of IRK tyrosine autophosphorylation." (PMID 33411692, 2021).